RB1 (RB transcriptional corepressor 1)
Diseases named in the same sentence as RB1 in open-access papers (continued):
Sharing a sentence is not in itself a finding about the gene and the disease.
leukemia (29 papers, 2008 to 2026). A malignant (clonal) hematologic disorder, involving hematopoietic stem cells and characterized by the presence of primitive or atypical myeloid or lymphoid cells in the bone marrow and the blood. "On the other hand, the mutational alleles on IKZF1 (chr7:50382590, G>A, p.G158S) and RB1 (chr13:48409776, T>C) are extremely concentrated in relapsed leukemia cells, indicating these mutations raised during late phase of leukemia progress." (PMID 33408321, 2021). "In Burkitt’s lymphoma (Daudi) and leukemia cells, loss of RB1 function appears to be reversible, and IFN-β signaling induces RB1 gene expression or restores RB1 function by reducing its phosphorylation." (PMID 37182173, 2023). "Validated targets concentrated on key leukemia-related genes like PTEN, BCL2L11, CDKN1A, CCND1, RB1, E2F1, and TGFBR2." (PMID 42123456, 2026). "As expected, several previously reported genes with abnormal methylation in leukemias such as CPEB1, BLK, FLT3, ZCCHC7, EBF1, HDACs, IKZF1, RB1, CDK6, DOCK5, DPP10, MUC4, JAKs, KIT, KRAS, LINC01013, MAD1L1, NOTCH1, and STATs, among others, were also detected." (PMID 41226303, 2025). "In leukemia and lymphoma, PRMT5 silences RB family members (RB1, RBL1, and RBL2) via hypermethylation of H3R8 and H4R3, thereby disabling RB-mediated cell cycle control and promoting proliferation." (PMID 41204384, 2025). "Late-Pro leukemias were also significantly enriched for homozygous deletions of CDKN2A/B and RB1 (P = 0.0013 and 0.0047)." (PMID 37337105, 2023).
endometrial cancer (28 papers, 2000 to 2025). Primary or metastatic malignant neoplasm involving the endometrium (mucous membrane that lines the endometrial cavity). "Meanwhile, PRCA was selected as the primary disease model for functional validation of 6MP‐based collateral lethality owing to the high prevalence of RB1 CN deletions in this cancer type, as opposed to the predominance of RB1 mutations observed in other cancers such as breast or endometrial cancer." (PMID 40904703, 2025).
liver cancer (28 papers, 2007 to 2025). An epithelial or non-epithelial malignant neoplasm that arises from the liver. "The gene included in this region is RB1, a well-known tumor suppressor that was highly associated with liver cancer." (PMID 31660973, 2019). "Mutations or alterations in the RB1 gene can lead to cancer development, including liver cancer." (PMID 37240140, 2023). "Possible therapies for the overexpressed kinases include CDK4/CDK6 inhibitors, such as Palbociclib, which has been shown effective in human liver cancer cell lines and mouse models with intact tumor suppressor Retinoblastoma (Rb1)." (PMID 35433463, 2022). "Louandre found in sorafenib-treated liver cancer cells in which the downregulation of RB1 promoted the occurrence of ferroptosis." (PMID 34868262, 2021). "Some examples are as follows: Rg3 and Rh2 both decrease viability and invasiveness of A549 human NSCLC cells while stimulating apoptosis significantly; Rb1 was reported to inhibit migration and invasion of liver cancer cells via Nrf2 regulation." (PMID 32774433, 2020). "The RB1 gene is considered a key factor in liver cancer, and studies have shown that sorafenib, as the only first-line treatment for advanced liver cancer, can induce ferroptosis in liver cancer." (PMID 41394869, 2025). "Importantly, recent studies have shown that therapy-resistant cancers, in which RB1 inactivation most commonly occurs, are vulnerable to ferroptosis, and RB1 knockdown appears to enhance the sensitivity of liver cancer cells to sorafenib-induced ferroptosis in vitro." (PMID 36928314, 2023). "In the liver cancer (LIHC), the well-predicted genes are RB1 and TGFβ2." (PMID 34556802, 2021).
triple-negative breast carcinoma (28 papers, 2014 to 2025). An invasive breast carcinoma which is negative for expression of estrogen receptor (ER), progesterone receptor (PR), and human epidermal growth factor receptor 2 (HER2). "Functional loss of RB1 is a common genetic alteration in triple-negative breast cancer (TNBC) and is associated with poor response to targeted therapies, including CDK4/6 inhibitors." (PMID 41285729, 2025). "Triple-negative breast cancer (TNBC) provides an important parallel to the findings for RB1 loss in HGSC." (PMID 38837893, 2024). "Similar results were observed in lung, prostate, and triple-negative breast cancer cells harboring natural RB1 loss-of-function mutations or deletion." (PMID 37502925, 2023). "Knockdown of ZNF703 in triple-negative breast cancer cells was shown to inhibit the expression of cyclin D1, CDK4, CDK6, and E2F1 and upregulation of Rb1." (PMID 37686244, 2023). "Moreover, RB1 loss (in combination with impaired BRCA-mutant signature and high SLFN11 expression) was highly predictive for the response of patient-derived xenografts of triple-negative breast cancer to irinotecan (SN-38 is the active metabolite of irinotecan)." (PMID 33591981, 2021). "Although defects in the RB1 tumour suppressor are one of the more common driver alterations found in triple-negative breast cancer (TNBC), therapeutic approaches that exploit this have not been identified." (PMID 29915391, 2018).
neuroendocrine carcinoma (27 papers, 2013 to 2026). A malignant neuroendocrine neoplasm composed of cells containing secretory granules that stain positive for NSE and chromogranin. "An inactivation of RB1 was reported to play a pivotal role in carcinogenesis of neuroendocrine carcinomas, and Rb1 protein loss was proposed to be a characteristic in gastroenteropancreatic and pulmonary neuroendocrine carcinomas." (PMID 32556556, 2021). "RB1 loss is one of the most critical events in neuroendocrine carcinoma, but the mechanism by which RB1 contributes to NE phenotype is largely unclear." (PMID 32039001, 2019). "Mutations in CDKN2A or RB1 co-occurring with SMARCA4 or ARID1A have been reported previously in olfactory neuroblastoma and neuroendocrine carcinoma." (PMID 38201285, 2023). "RB1 mutation is common in SCLC, while neuroendocrine cancer also has certain biological characteristics of SCLC." (PMID 32508051, 2020). "To gain a better understanding of these in vivo effects, we used a defined preclinical model of neuroendocrine cancer, Rb1+/− mice." (PMID 23454836, 2013). "p16 overexpression is also known to be induced by deregulation of RB1 in neuroendocrine carcinomas." (PMID 32556556, 2021). "Thus, RB1 inactivation plays a key role in the development of neuroendocrine carcinoma." (PMID 40491286, 2026).
ocular tumors (24 papers, 2012 to 2025). "Differentiating between germline and somatic RB1 mutations is clinically crucial, since patients carrying germline alterations require lifelong surveillance for both secondary ocular tumors and late-onset systemic malignancies." (PMID 41465072, 2025). "The RB1 tumor suppressor gene is initially characterized based on the germline predisposition of the pediatric eye tumor." (PMID 38672640, 2024). "The medical history revealed that enucleation was performed at the age of three years due to an eye tumor, and genetic counseling was recommended due to the very likely presence of a pathogenic RB1 variant as mosaicism." (PMID 37884744, 2023). "rb1 canonically functions to regulate the cell cycle, and when mutated the loss of rb1-mediated cell cycle control elicits childhood ocular tumor formation." (PMID 23209449, 2012). "However, diverse somatic mutations of the alternate parental copy of RB1 were identified in the two tumours (PD34258 (right eye tumour), PD37502 (left eye tumour))." (PMID 33670346, 2021). "Germline RB1 mutation carriers are also at an increased lifetime risk of non-ocular tumours." (PMID 33670346, 2021). "In humans the rb1 nt1960+1 mutation, which is identical to the zebrafish rb1te226a mutation, causes ocular tumors, raising the possibility that zebrafish rb1 mutants might also develop tumors as juveniles." (PMID 23209449, 2012). "Mosaic double rb1/rbl1 knockout tadpoles (MDKO tadpoles) rapidly developed externally visible eye tumors as early as 36 days post-injection." (PMID 27739525, 2016). "Children with biallelic germline or sporadic inactivation of rb1 are likely to form ocular tumors during early childhood." (PMID 23209449, 2012). "However, rb1 mutants fail to inflate a functional swim bladder, and die ∼7 days post fertilization, precluding the analysis of ocular tumors in juveniles." (PMID 23209449, 2012). "There is an active clinical trial evaluating whether certain germline RB1 mutations affect the risk of secondary non-ocular tumors (ClinicalTrials.gov NCT00342797), but this is not specific to ocular prognostication." (PMID 31835688, 2019).
prostate adenocarcinoma (23 papers, 2017 to 2025). "We previously demonstrated that co-loss of Pten and Rb1 (DKO mice) genes promotes a shift from prostate adenocarcinoma to a NE-like PCa phenotype that is resistant to ARSI." (PMID 40832297, 2025). "A further finding corroborated this in an in vivo mouse model, highlighting that RB1 loss promotes the lineage plasticity and metastasis of prostate adenocarcinoma, which is initiated by PTEN mutation." (PMID 39682746, 2024). "While complete inactivation of Pten alone in mouse prostate leads to indolent prostate adenocarcinoma that rarely metastasizes to distant organs, Rb1 loss drives lineage plasticity, metastasis, and lethality of prostate tumors initiated by Pten loss." (PMID 36928314, 2023). "Recently, the coordinated mono-allelic loss of BRCA2/RB1 on 13q was shown to evoke aggressive phenotypes in prostatic adenocarcinomas vulnerable to PARP inhibitor-based therapy." (PMID 35406559, 2022). "Rb1 loss causes lineage plasticity and metastasis of prostate adenocarcinoma, initiated by Pten mutation." (PMID 33299560, 2020). "Similarly, Rb1 loss promoted metastasis of prostate adenocarcinoma initiated by Pten mutation." (PMID 33591981, 2021). "It is noteworthy that alteration of the other pocket protein paralogues RBL1 and RBL2 is rare in both prostate adenocarcinoma and NEPC, suggesting loss of RB1 has a unique role in cancer lineage plasticity in the prostate." (PMID 35368709, 2022). "The frequency of RB1 alteration increases markedly in NEPC compared to advanced prostate adenocarcinoma." (PMID 35368709, 2022).